IL10 (interleukin 10)
Diseases named in the same sentence as IL10 in open-access papers (continued):
Sharing a sentence is not in itself a finding about the gene and the disease.
Parkinson disease (32 papers, 2015 to 2025). A progressive degenerative disorder of the central nervous system characterized by loss of dopamine producing neurons in the substantia nigra and the presence of Lewy bodies in the substantia nigra and locus coeruleus. "In contrast, B cells isolated from Parkinson’s disease patients at higher risk of dementia had greater cytokine (interleukin 6 and interleukin 10) responses following in vitro stimulation." (PMID 36993946, 2023). "Elevated levels of pro-inflammatory RANTES or MCP-1 and decreased levels of anti-inflammatory IL-10 were found to associate with Parkinsonism and a more rapid disease progression, indicated by longitudinal measurements of either MMSE or ADCS-ADL decline." (PMID 31559531, 2020). "The MPTP caused a remarkable decrease in basal protein levels of IL-10 in substantia nigra and corpus striatum in the Parkinson (P) group as compared to the Control (C) group (P<0.05)." (PMID 32489563, 2020). "The neuroprotective activity of Treg cells, through a mechanism that may involve IL-10 secretion, has been described in murine models of Parkinson's disease, HIV-1-associated neurodegeneration, amyotrophic lateral sclerosis and stroke." (PMID 34290279, 2021). "Our study shows that ILA830 decreases these proinflammatory cytokines in mice with MPTP-induced parkinsonism while increasing the anti-inflammatory cytokine IL-10." (PMID 40336061, 2025). "Consistently, in a mouse model of Parkinson’s disease (PD), IL-10 gene therapy has been shown to elicit immunomodulation with enhanced suppression of neuroinflammation associated with dopaminergic neuron survival." (PMID 40332510, 2025). "Like our MCR participants, AD patients have been shown to have weak expression of IL-10, and depressed levels of IL-10 have also been seen in pain and clinical symptoms in Parkinson’s disease." (PMID 37371414, 2023). "Patients with Parkinson’s disease had elevated frequencies of Th1 cells and serum levels of IL10 and IL17A as compared to healthy controls." (PMID 36038917, 2022). "The suppression of microglial activation by IL-10 is well established but this is the first time it has been shown in the context of brain repair for Parkinson’s disease." (PMID 34497719, 2021). "IL-10 basal protein levels were increased in mice treated with exercise and decreased in Parkinson +Exercise (PE) groups as compared with that in the Control (C) group." (PMID 32489563, 2020). "In conclusion, IL-10-eluting collagen hydrogels may have beneficial anti-inflammatory effects in the context of cellular brain repair therapies for Parkinson’s disease and should be investigated further." (PMID 34497719, 2021). "Interestingly, miR-190 was involved in neuroinflammation as its upregulation inhibited the expression of inducible nitric oxide synthase and other proinflammatory cytokines as IL-6, while it increased the expression of anti-inflammatory cytokines such as IL-10 in a Parkinson’s disease mouse model." (PMID 32531989, 2020). "Hence, a host of anti-inflammatory therapies have been tested using cell-based and rat models of PD to test the ability of various neuroinflammatory mediators such as Dexamethasone, aspirin, interleukin-10, and Minocycline to suppress the onset of Parkinson-like symptoms." (PMID 26576219, 2015). "Vitamin D supplementation (1 μg/kg vitamin D daily by intragastric gavage for 10 days) also attenuates neuroinflammation through the up-regulation of the anti-inflammatory cytokines (IL-10, IL-4, and TGF-β) mRNA in a Parkinson’s disease animal model." (PMID 35866081, 2022). "Also, adenoviral-mediated expression of human IL-10 in the striatum of mice subjected to MPTP (1-methyl-4-phenyl-1,2,3,6-tetrahydropyridine) neurotoxicant model of Parkinson’s disease decreased the neurodegenerative effect of MPTP administration." (PMID 27881137, 2016).
Parkinson disease (continued). "Notably, as the observed differences related to disease progression and Parkinsonism were biologically rational (inverse effects of pro-inflammatory RANTES and MCP-1 and anti-inflammatory IL-10), the results are likely to suggest biological pathways rather than coincidental type 1 errors." (PMID 31559531, 2020). "Interestingly, patients manifesting with Parkinsonism showed lower levels of IL-10, elevated levels of MCP-1, and a nonsignificant trend towards elevated levels of RANTES, suggesting that the clinical FTLD phenotype with Parkinsonism is associated with a disadvantageous pro-inflammatory profile." (PMID 31559531, 2020). "FTLD patients with Parkinsonism showed significantly higher levels of plasma MCP-1 (U = 345, p = 0.030) and, conversely, lower levels of the anti-inflammatory IL-10 (U = 404, p = 0.016) compared to FTLD patients without Parkinsonism." (PMID 31559531, 2020).
renal cell carcinoma (32 papers, 1999 to 2025). "In a study of advanced renal cell carcinoma, it was found that increased levels of IL-10 are associated with the potential development of metastasis." (PMID 40725135, 2025). "In human renal cell carcinoma specimens, IL-10 is associated with a poor prognosis, and patients with elevated IL-10 serum levels have a worse outcome after surgery." (PMID 28099146, 2017). "It should be noted that some studies have found that TGF-β secretion in B cells is linked to IL-10 expression, indicating that complex network functions among immunosuppressive cytokines secreted by carcinoma of renal cells may occur." (PMID 33767709, 2021). "Inverse associations were found between the frequency of IL-10-producing B cells and the pro-inflammatory cytokine-producing T cells, as well as the proliferation of T cells, thus it is hypothesized that in renal cell carcinoma, IL-10-producing B cells can contribute to T cell immunosuppression." (PMID 33767709, 2021). "PEGylated IL-10 monotherapy induced objective tumor responses in patients with renal cell cancer (RCC)." (PMID 37398660, 2023). "Studies have revealed that macrophages infiltrating renal cell carcinoma secrete immunosuppressive cytokines IL-10 and cell chemokine ligand 2 (a proinflammatory chemokine)." (PMID 33767709, 2021). "In sum, the important role of Bregs in renal cell carcinoma is to induce the development of regulatory T cells through the production of IL-10, which then plays a role in immune escape." (PMID 33767709, 2021). "Another antiviral agent - ribavirin was also reported as an immune response inducer in the renal cell carcinoma lines through the downregulation of IL-10 expression and the upregulation of TGF-β expression." (PMID 28344640, 2017). "Recently, therapy with PEGylated-IL-10 and anti-PD-1 monoclonal antibody (pembrolizumab or nivolumab) has shown encouraging results in a phase 1b clinical trial conducted on advanced refractory renal cell carcinoma and non-small-cell carcinoma patients." (PMID 37359549, 2023). "While it is known that IL-10 is one of the cytokines activating STAT3—a well-known activator of transcription that plays an important role of renal cell carcinoma development—increased STAT3 activation correlates with both advanced metastatic disease and worse survival in RCC." (PMID 37108073, 2023). "In the model of BALB/c mice with renal cell carcinoma (RCC), circulating levels of M2-like markers and pro-angiogenic cytokines, including IL-4, IL-10, IL-13, and VEGF-A, were reduced in endostatin-treated animals in comparison with non-treated control." (PMID 34209679, 2021). "A recent study has suggested that microRNA let-7d inhibits M2 polarization of macrophages and subsequent tumor progression by decreasing mRNA expression levels of IL-10 in renal cell carcinoma (RCC)." (PMID 34625124, 2021). "The initiation and progression of renal cell carcinoma (RCC) is promoted by BMP-6-mediated IL-10 expression, which regulates M2 polarization." (PMID 28915705, 2017). "Soluble levels of PD-L1, IL-10, and CD163 have been reported as potential biomarkers in various cancers, although the prognostic value in renal cell carcinoma (RCC) has to be further elucidated." (PMID 35204426, 2022). "A phase I study demonstrated safety of a vaccine against renal cell carcinoma (RCC) containing tumor cells expressing RCC26/IL-7/CD80; while they did not observe increased Th1 specific immune responses, they did find higher levels of Th2 mediated IL-10 expression in patients who responded." (PMID 25268164, 2014). "However, the treatment of DCs with supernatant of RCC-10 (renal cell carcinoma cells), resulted in a reduction in the expression of maturation markers, but did not affect IL-10 production in response to stimulation with TNFα, IFNα and poly I:C." (PMID 22125641, 2011).
renal cell carcinoma (continued). "In renal cell carcinoma (RCC), TAMs produce high levels of lipid-derived 15-hydroxyeicosatetraenoic acid through the enzymatic activity of 15-lipoxygenase 2 (15-LOX2), which positively correlates with CCL2 and IL-10 secretion, supporting pro-tumoral inflammation." (PMID 32823961, 2020).
abortion (31 papers, 2012 to 2025). the ending of pregnancy by removing a fetus or embryo before it can survive outside the uterus. "The administration of exogenous IL-10 prevents fetal loss in abortion-prone mice, whereas the depletion of IL-10 promotes abortion." (PMID 34298914, 2021). "Previous murine studies have shown that splenic Bregs can rescue pregnancies in abortion-prone models, and a clinical study has revealed that deficiency in circulating IL-10-producing Bregs is correlated with higher risk of spontaneous abortions." (PMID 31921160, 2019). "In a well-known mouse cross that is prone to spontaneous abortion, a deficiency of IL10 has been demonstrated to alter the net fetal number and outcome." (PMID 27335593, 2016). "Several studies have analyzed the possible correlations between 3 polymorphisms present at the level of the promoter of the codifying gene for IL10 and the abortion disease, namely polymorphisms -592C/A, -819C/T and -1082A/G." (PMID 25469134, 2014). "The cumulative evidence suggests that Treg cells and Th2 cells promote allograft tolerance by repressing Th1 and Th17 cells that are accountable for spontaneous abortion, which can secrete IL-10, TGF-β and IL-4 cytokines, respectively." (PMID 36816578, 2023). "A higher M1/M2 ratio of dMφs was demonstrated in spontaneous abortion, which manifested a higher expression of M1-associated markers (CD86, CD80, and IL-1β) and lower expression of M2-associated markers (CD209, CD206, IL-10, and TGF-β1." (PMID 37033974, 2023). "The abortion-prone mouse model exhibits a dysregulated cytokine balance and downregulated levels of IL-10 and IL-4 in feto-placental units." (PMID 34298914, 2021). "We found the serum levels of IL-10, a representation of Th1 cytokines, were significantly lower in abortion-prone mice model whereas the serum level of TNF-α and INF-γ, a representation of Th2 cytokines, were significantly higher." (PMID 33763083, 2021). "Peritoneal CD19+IL-10+ cells were also shown to increase throughout normal pregnancy whereas a significant reduction was seen in abortion-prone pregnant females." (PMID 31921160, 2019). "TLR9 and IL-10 SNPs have been found to play critical roles in the development of spontaneous abortion." (PMID 30116270, 2018). "In accordance to the augmented number of Treg cells, we found elevated TGF-β and IL-10 levels in decidual tissue of abortion-prone females that received hCG-treated BMDCs as compared to females that received mature BMDCs." (PMID 27895621, 2016). "Further support for IL-10 and its role in preventing spontaneous abortion was demonstrated in mice administered rIL-17 transvaginally on gestational day 1 which decreased decidual IL-10 levels and induced abortion." (PMID 24904596, 2014). "Interestingly, in a spontaneous abortion mouse model, the in vivo injection of recombinant IFN-τ can also decrease fetal loss by elevating IL-10 production." (PMID 40872670, 2025). "While it decreases the levels of proinflammatory cytokines such as progesterone, IL-6, and TNF-α, which are frequently used in the treatment of threatened abortion, it increases the levels of the anti-inflammatory cytokine IL-10 in proportion to the administered dose." (PMID 34909296, 2021). "Moreover, the adoptive transfer of IL-10-producing B cells mitigated the incidence of abortion in abortion-prone mice." (PMID 34298914, 2021). "To determine whether tregitope treatment restores the Th1/Th2 balance during pregnancy in abortion-prone mice, we examined the levels of IL-2, IL-4, IL-10, IFNγ and TGFβ1 cytokines in blood sera." (PMID 32601347, 2020). "In normal pregnancy, the levels of serum Th2 cytokines IL-6 and IL-10 were found to be significantly higher than in patients with recurrent spontaneous abortion, while levels of serum Th1 cytokine IFN-γ is significantly elevated in recurrent spontaneous abortion." (PMID 31649614, 2019).
abortion (continued). "Moreover, other studies have suggested that macrophages in decidual tissues in early pregnancy secrete large amounts of IL-10; compared with those of normal pregnant women, IL-10 levels in decidual tissues of women with spontaneous abortion are decreased." (PMID 31043168, 2019). "However, predominant Th2 type immunity was found in abortion cases, and the typical Th2 type cytokines IL-4 and IL-10 KO mice are fertile." (PMID 23028860, 2012). "On the other hand, there is a strong correlation between spontaneous abortion and increased production of proinflammatory factors, such as cytokines TNF-α and IFN-γ, and conversely, a reduction in the anti-inflammatory cytokine IL-10 is also associated with spontaneous abortion." (PMID 37760110, 2023). "However, we believe that the delivered amount of SGS peptide might induce, as observed in this study, increased concentration of the IL-10 in blood sera, which in turn might prompt Tregs and contribute to improved pregnancy outcomes in abortion-prone mice." (PMID 34298914, 2021). "Several studies have associated IL-10 deficiency to recurrent spontaneous abortion; however, the mechanisms that may lead to poor IL-10 production at the maternal–fetal interface are not well understood." (PMID 24260517, 2013). "In our study, the increase in Th1 and decrease in IL-10 can be also explained by the status of GDM mothers with multiple background of recurrent miscarriage and spontaneous abortion." (PMID 30539027, 2018). "The frequencies and cell numbers of peritoneal and splenic CD19+IL-10+ and CD19+CD5+IL-10+PC1+ cells were assessed in virgin as well as normal pregnant (NP) and abortion-prone (AP) females during the course of gestation." (PMID 29868008, 2018). "This study has proven a possible association of polymorphism -819 C/T and the increased frequency of recurrent abortions and the lack of association between polymorphisms IL10-592C/A, -1082A/G, IL6-174G/C and the abortion disease in the studied group." (PMID 25469134, 2014). "In this study, we investigate the serum levels of inhibitory cytokines IL-35, IL-10 and TGF-β in both normal pregnancies and non-pregnant females, and whether IL-35 is associated with the pathogenesis of recurrent spontaneous abortion." (PMID 26042836, 2015). "The levels of IL-35, IL-10, TGF-β, estradiol (E2), unconjugated estriol (uE3) and AFP were analyzed in 120 normal pregnancies, 40 women suffering recurrent spontaneous abortion, 40 postpartum healthy women and 40 non-pregnant women by enzyme-linked immunosorbent assay (ELISA)." (PMID 26042836, 2015).
leptospirosis (31 papers, 2010 to 2025). A contagious bacterial infection caused by spirochetes of the genus Leptospira. "The immunoprotective role of IL-10 during leptospirosis is to mitigate the deleterious effects caused by the increase in pro-inflammatory cytokines, such as interleukin 1 β (IL-1β), which is related to organ failure in infected hosts." (PMID 34070451, 2021). "By contrast, other studies showed that low IL-10/TNF-α ratio was associated with leptospirosis, severe disease and fatal outcomes." (PMID 32264832, 2020). "Among patients hospitalized with severe leptospirosis, increased concentrations of IL-6, IL-8, IL-10 and IFN-γ were associated with fatal outcomes in univariate analysis." (PMID 24069500, 2013). "In addition, previous studies in leptospirosis have shown a significant association between IL-10 and fatal outcomes." (PMID 35919644, 2022). "The production of IL-10 has been associated with the risk of death in humans with leptospirosis; however, a study conducted on exposed and asymptomatic humans associated the production of this cytokine with the control of the inflammatory response and survival." (PMID 35203344, 2022). "The inhibition of IL-10 production might play an important role in decreasing the risk of fatal outcomes in leptospirosis." (PMID 35919644, 2022). "Progression from a non-specific immune response to an acquired immune response with Th2 predominance, including inhibition of Th1 with excessive production of IL-10, plays an important immune-pathogenic role in estimating the severity and mortality rate of leptospirosis." (PMID 35919644, 2022). "High IL-10/TNF-α ratio was associated with leptospirosis and fatal outcomes." (PMID 32264832, 2020). "Interestingly, early enhanced IL-10 expression has been shown in other murine models of leptospirosis and has been linked to death in humans and hamsters infected with leptospires." (PMID 25032961, 2014). "Notably, we also found that a high ratio of IL-10 to TNF-α was associated with death from leptospirosis, driven predominantly by IL-10 levels." (PMID 24069500, 2013). "Furthermore, previous studies of patients with leptospirosis had also identified higher levels of IL-10 to be associated with death." (PMID 24069500, 2013). "Of additional relevance, M2 macrophages can secrete IL-10, illustrating another immune component that should be investigated in the deer mouse model of leptospirosis." (PMID 40562727, 2025). "TNF-α, proinflammatory IL-6, chemokine IL-8, and anti-inflammatory IL-10 were known to play important roles in the pathogenesis of leptospirosis." (PMID 40861768, 2025). "A previous systematic review showed elevated levels of cytokines (IL-1β, IL-2, IL-4, IL-6, IL-8, IL-10, TNFα) in severe human leptospirosis compared with mild leptospirosis." (PMID 39729468, 2024). "In patients with severe leptospirosis, elevated levels of IL-6, IL-10, and TNF-α have been observed during a cytokine storm." (PMID 38398036, 2024). "TLR2 involvement during the pathogenesis response against leptospirosis was observed through the decrease of IL1β, TNFα, IL6, NFκB, and IL10 secretion/expression due to deficient/knocked down of the TLR2 receptors." (PMID 39729468, 2024). "In conclusion, the results show that TNF-α and IL-10 significantly increased in severe leptospirosis and IL-10 is significantly higher in fatal cases." (PMID 35919644, 2022). "In studies of patients with multiple clinical manifestations with leptospirosis, the severity of the clinical picture has been associated with various serum cytokines levels, such as TNF-α, IL-10, and IL-6, but this conclusion remains controversial." (PMID 35203344, 2022). "Recommendations: The use of specific anti-inflammatory cytokine products such as IL-10 will shed light on the treatment and better prognosis of leptospirosis patients [delete]." (PMID 35919644, 2022).